INS (insulin)
Diseases named in the same sentence as INS in open-access papers (continued):
Sharing a sentence is not in itself a finding about the gene and the disease.
diabetes (continued). "The median times to resolution of acidemia and ketoacidosis were both shorter in the group of dogs treated with IM insulin lispro, although these differences were not significant (P = 0.06 and P = 0.09, respectively)." (PMID 33195532, 2020). "Although there were higher proportions of insulin therapy and lower proportions of lipid-lowering drugs in the early-onset diabetes group, these differences were not significant." (PMID 32614772, 2020). "Postoperatively, intravenous boluses of insulin were administered to 12.28% of patients without diabetes and to 13.35% of patients with diabetes (P=0.43)." (PMID 33118731, 2020). "Variables that were not notable predictors of readmission were diabetes without insulin use, prolonged operating time (defined as mean + 1 SD), male gender, age, BMI, use of regional anesthesia, and a discharge to home." (PMID 33969951, 2020). "Increased PPG is also followed by a rise in postprandial insulin in people who do not have diabetes." (PMID 32471238, 2020). "Dyslipidemia is a major CVD risk factor for both healthy subjects and patients with type 2 diabetes mellitus (T2DM), accounting for 72–85% of diabetics, but it is also very common in insulin resistant subjects who do not yet have established T2DM." (PMID 33291645, 2020). "Using slow-acting insulin is not inferior to using fast-acting insulin in the maintenance of partially insulin-controlled moderate diabetes in rats." (PMID 32813772, 2020). "Hyperglycemia in diabetes results from the inability of the pancreas to produce insulin or lack of effective use of insulin by the body cells." (PMID 32560082, 2020). "We acknowledge the limitation of the small sample size and the lack of the assessment of the prevalence of diabetes due to the lack of blood sugar and fasting insulin measurement." (PMID 32917002, 2020). "Insulin-requiring GDM was defined as no claims for diabetes mellitus and a fasting blood glucose level of < 126 mg/dL before pregnancy, and initiation of insulin treatment during pregnancy." (PMID 32807828, 2020). "In contrast to GCK-MODY, there is impairment of first and second-phase insulin secretion in individuals with HNF1A mutations, resulting more often in overt diabetes as opposed to the mild hyperglycemia seen in the first." (PMID 32528556, 2020). "Diabetes mellitus is a disease that manifests when the pancreas does not produce enough insulin (type I) or when the body cannot effectively use the insulin it produces (type II)." (PMID 32365648, 2020). "This retrospective cohort study examined patients aged 65 years and older with diabetes not previously requiring insulin." (PMID 32207832, 2020). "T1D, also called diabetes mellitus type 1, is a form of diabetes mellitus in which pancreas fails to produce insulin." (PMID 32025210, 2020). "Diabetes induced a decrease (p < 0.05) at 1452 cm-1 and 836 cm-1 bands compared with non-diabetic rats, however, insulin-treated diabetic reverted this alteration in both bands (respectively)." (PMID 32182246, 2020). "On the day of diabetes induction, no marked differences were observed in serum insulin and glucose levels among all groups of rats." (PMID 33187275, 2020). "During diabetes mellitus, an increase in blood glucose is occurred due to a lack of insulin secretion or insulin dysfunction or both." (PMID 32831835, 2020). "This drug does not cause impaired glucose tolerance, pre-diabetes, or diabetes, suggesting that TRPM3 is not essential for insulin secretion." (PMID 32168890, 2020). "FSG, insulin and HOMA-IR were significantly increased in diabetes group compared to control group." (PMID 33081726, 2020). "In a rat model of diabetes, MenSC-derived EVs were tracked in, and enhanced the number of pancreatic β cell islets and raised serum insulin, without impact on non-fasting blood glucose." (PMID 32742977, 2020). "Among participants with non–insulin-treated T2DM, the mean duration of known diabetes was 3 years." (PMID 31720686, 2020).
diabetes (continued). "Indeed, some reports indicated that LC induced life-threatening ketoacidosis in subjects with T1DM, who intentionally reduced daily dosage of insulin injection or developed to euglycemic diabetic ketoacidosis." (PMID 33362717, 2020). "One of the limitations of our study is that our findings cannot be extrapolated to proteinuric T2DM patients, since our insulin-treated participants were at relatively early stages of diabetes-related CKD or without it." (PMID 32267348, 2020). "The long-term insulin therapy for type 1 diabetes mellitus (T1DM) fails to achieve optimal glycemic control and avoid adverse events simultaneously." (PMID 33102605, 2020). "Current therapeutic methods to treat diabetes typically include oral hypoglycemic drugs and insulin; however, they are not a real “cure” for diabetes and not effective for improving a patient’s condition." (PMID 32708290, 2020). "Twelve months after bariatric surgery, 9.1% of the patients had diabetes (3% insulin treated and 6.1% non-insulin treated), 6% dyslipidemia, and 12.9% hypertension." (PMID 32806629, 2020). "In our study, we explore the characteristics of insulin use by examining a large multi-institutional patient repository and we compare clinical outcomes between patients with and without diabetes as a function of insulin use." (PMID 33118731, 2020). "In contrast, females did not adequately adjust their insulin sensitivity, resulting in transient hyperglycemia coinciding with hypoinsulinemia, which is characteristic of diabetes progression." (PMID 31996693, 2020). "Although, Humalog U-200 is a practical alternative regimen to people with diabetes who take higher doses of rapid-acting (e.g. >0.5 units/kg), post-marketing surveillance or real-world evidence assessing the use of U-200 insulin in routine practice is lacking." (PMID 32002193, 2020). "Four programs cover T1D with no blood glucose monitoring restriction, and only one state covers both type 1 and insulin-requiring diabetes with no blood glucose restriction." (PMID 31596132, 2020). "The inclusion of one sample of D+I animals in the non-diabetic control group is expected, considering that insulin is a gold-standard treatment of diabetes." (PMID 32182246, 2020). "Although PAI-1 is a transcriptional target of insulin signaling in multiple tissue/cell types, PAI-1 expression is elevated in Type 1 and 2 diabetes and in diabetic animal models with no insulin treatment." (PMID 32993026, 2020). "Insulin, which modulates the production/release of TNF‐a, IL‐1b and P‐selectin in diabetic rats, was also reported to affect pulmonary function and respiratory symptoms in patients with diabetes." (PMID 33145961, 2020). "The importance of research in the fields of glucose homeostasis, insulin and diabetes has not faded." (PMID 32872570, 2020). "After adjusting for multiple confounding factors, including gender, age, education, duration of diabetes, baseline insulin regimen, and baseline FBG and PBG, the number of diabetes education courses that the patients completed was still related to their glycemic control." (PMID 32141838, 2020). "In addition, IL-1β and TNFα treatments, which mimic the inflammation condition of diabetes, decreased SIRT3 expression in a mouse insulin-producing β cell line (INS1)." (PMID 32722262, 2020). "This study fills the current gap in knowledge not addressed by the Diabetes Remission Clinical Trial, which focused on those diagnosed with type 2 diabetes for less than 6 years who were not treated with insulin." (PMID 32049634, 2020). "Subcutaneous insulin was utilized in 18.46% of patients without diabetes and 24.56% of patients with diabetes (P=0.0003)." (PMID 33118731, 2020). "The incidence of DME after 10 years of diabetes is 20.1% in type 1 diabetics, 25.4% in type 2 diabetics requiring insulin, and 13.9% in type 2 diabetics not requiring insulin, as reported by the Wisconsin Epidemiologic Study of Diabetic Retinopathy (WESDR)." (PMID 32295293, 2020).
diabetes (continued). "To determine whether STZ-induced diabetes modified the expression of NF200, we assessed changes in intensity of NF200 immunostaining in relation to insulin+ islet volume and time after treatment." (PMID 33036983, 2020). "Strikingly, chronic fenofibrate treatment completely prevents the spontaneous sequential hypertrophy and atrophy of pancreatic islets from obese diabetes-prone Otsuka Long Evans Tokushima Fatty (OLETF) rats, decreases body weight and visceral fat, and improves insulin action in skeletal muscle." (PMID 32708786, 2020). "In addition to insulin, oral antidiabetic drugs (PAD) are also used to treat diabetes with metformin being one of the most commonly prescribed." (PMID 33585194, 2020). "We demonstrated that after 3‐months of diabetes the percentage of 3‐MC decreased by approximately 13%, and this decrease was not significantly normalized following 1‐month of insulin treatment." (PMID 33200530, 2020). "Previously, diabetes is well known to induce pulmonary dysfunction, such as reducing lung volumes and compliance and increasing in airway resistance, which is related to insulin resistance and non-enzymatic glycosylation of lung proteins." (PMID 33002109, 2020). "The third child, however, diagnosed with diabetes at 18 months whose pancreas was analysed within 2 weeks of diagnosis of diabetes displayed normal insulin staining with no morphological abnormality." (PMID 32839884, 2020). "Diabetes is defined as abnormalities in blood sugar control overtime, which is characterized by hyperglycemia as a consequence of total lack of insulin secretion or lack of insulin activity in target tissues or both." (PMID 31993169, 2020). "The diabetes cohort recruited to our study, although having increased risk of PAD (e.g. higher BMI, diabetes, insulin use), did not demonstrate overt clinical signs or symptoms of PAD and MAC." (PMID 32398142, 2020). "First of all, many physicians focus on controlling hyperglycemia in diabetes, while insulin resistance and lack of insulin production remain untouched." (PMID 32117245, 2020). "Thus, in the Diabetes Control and Complications Trial (DCTT), patients with poorly controlled insulin-treated T1DM were found to have low HDL levels." (PMID 32708413, 2020). "Type 2 diabetes mellitus is a metabolic disease characterized by chronic hyperglycemia due to insulin resistance, or the relative absence of the hormone." (PMID 32752292, 2020). "Diabetes mainly developed due to lack of insulin release from the β cells and the abnormally high production of glucagon from the α cells of pancreas." (PMID 32815547, 2020). "During the first week of age, the OVE26 mice develop diabetes and they can survive over one year with no insulin treatment." (PMID 32566684, 2020). "The epidemic metabolic disorder, diabetes mellitus (DM) is characterized by high blood glucose where the patient cannot produce adequate insulin, or body cells do not respond to glucose produced by β-cells in the pancreas." (PMID 32207527, 2020). "Additionally, allicin decreased hyperglycemia, improved insulin levels, and prevented changes in (GLUT4) and IRSs expression induced by diabetes." (PMID 33203103, 2020). "DM type I is caused by an autoimmune destruction of pancreatic β-cells, resulting in a lack of insulin and diabetes." (PMID 32722164, 2020). "Diabetes mellitus (DM) is a chronic metabolic disease characterized by hyperglycemia accompanied by greater or lesser impairment in the metabolism of carbohydrates, lipids and proteins resulting from defects in insulin secretion, insulin action, or both (ADA, 2014 ▶)." (PMID 32850290, 2020). "Individuals with this diabetes phenotype are typically treated with insulin as a result of their severe hyperglycaemia but do not develop keto-acidosis upon insulin withdrawal." (PMID 33302939, 2020). "Although SCGN is not co-released with insulin, plasma concentrations have been found to be increased in type 2 diabetes mellitus patients." (PMID 32708966, 2020).
diabetes (continued). "Insulin levels are usually measured for persons with diabetes mellitus not suitable for the general population." (PMID 33028338, 2020). "This previous study evaluated 854 noninstitutionalized patients with diabetes who were more than 15 years old and were treated with insulin or oral hypoglycemic agents." (PMID 32071329, 2020). "Diabetes mellitus (DM) is a polygenic disorder, in which body does not deliver enough of the insulin, and/or body develops defects in insulin action which finally causes elevated amount of sugar in bloodstream." (PMID 33118125, 2020). "Furthermore, the analysis concerned the diabetes duration, age at the T1D onset, and type of treatment—multiple daily insulin injections (MDI) or continuous subcutaneous insulin infusion (CSII)." (PMID 33294460, 2020). "These questions need to be further explored in order to highlight or confirm the role of glucagon in diabetes development, since GLP1 is broadly used as a drug to stimulate insulin secretion, which in the long run could actually impair beta-cell function." (PMID 33294459, 2020). "During the study period, 23 children were diagnosed with other types of diabetes (11 with maturity-onset diabetes of the young 2, six with type 2, and six were insulin dependent, but autoantibody negative—not included into the present analysis as T1D)." (PMID 32849272, 2020). "Volunteers without diabetes aged 21–50 years completed a 3-day food diary and underwent an oral glucose tolerance test to estimate insulin sensitivity (n = 44)." (PMID 32079066, 2020). "As part of diabetes therapy, intensification was intended as the addition of a new drug, the increase in the dosage of the existing therapy, or the initiation of insulin in the presence of non-target HBA1c values." (PMID 32565924, 2020). "Diabetes mellitus (DM) is a metabolic condition where there is a lack of insulin production (type 1) or a combination of impaired insulin secretion and action (type 2)." (PMID 32698397, 2020). "This high palmitoleic acid improved insulin sensitivity among type 2 diabetes mellitus patients and prevented reduced insulin sensitivity in non-diabetic individuals, which adversely support the finding from patients with high levels of HOMA2-%S." (PMID 32357546, 2020). "We evaluated the women who subsequently developed diabetes with dietary modification (GDM-1) (n = 125) and with insulin therapy (GDM-2) (n = 21), as well as the women who developed gestational hypertension (GH) (n = 113) and preeclampsia (PE) (n = 24), compared to the healthy controls." (PMID 32599847, 2020). "The variability of protein isoforms of the insulin signalling cascade (IRecs, IRS, PI3K, and AKT) and of diabetes phenotypes, mainly in T2D, is partially due to genetic variations and may be related to specific tissue resistance differences." (PMID 32377524, 2020). "The ability of insulin to restore circadian rhythm through BMAL1 and CLOCK genes may facilitate re-epithelialization, as these rhythms may be disturbed in diabetes." (PMID 32194500, 2020). "STZ-induced diabetes significantly increased TG levels compared with the controls (P-value<0.05), and treatment with insulin and encapsulated INPs did not have a significant effect on this level (P-value>0.05)." (PMID 32695298, 2020). "High blood sugar levels lead to a condition called hyperglycemia when insulin is not provided to utilize glucose diabetes." (PMID 32984558, 2020). "GDM is defined as a transitory form of diabetes induced by insulin resistance accompanied by a low/absent pancreatic beta-cell compensatory adaptation to the increased insulin demand." (PMID 32604801, 2020). "Our data also showed that compensatory transcription of a functional insulin gene in homozygous mice with a deletion in the Ins1 or Ins2 promoter did not lead to diabetes." (PMID 32546815, 2020).
diabetes (continued). "The final progression of the obese, prediabetic individual to overt diabetes is synonymous with a decline in insulin secretion without any worsening of insulin resistance." (PMID 32397353, 2020). "High-dose insulin treatment attenuated small nerve fiber damage assessed by Hargreaves' test and intraepidermal nerve fiber density compared to untreated diabetes and low-dose insulin; however, neuropathy was not completely prevented by tight glycemic control." (PMID 32832565, 2020). "Women with T2DM also have significantly higher fasting blood insulin levels than women without prediabetes/diabetes." (PMID 32733043, 2020). "The overall reduction of diabetes-related costs through periodontal treatment seems to be largely attributable to patients receiving insulin but not to patients receiving metformin or other oral blood glucose-lowering drugs." (PMID 33099508, 2020). "Only 464 (40.98%) of the patients without diabetes received continuous insulin infusion postoperatively." (PMID 33118731, 2020). "In subjects without diabetes and cardiovascular diseases, asparagine was inversely correlated with fasting insulin and insulin resistance while aspartate was inversely correlated with plasma glucose." (PMID 33092635, 2020). "Together, our findings show a regulatory role of AIM2, mediated by IL-18, in shaping gut microbiota and reducing bacterial translocation and proinflammatory response against insulin-producing β cells, which ultimately results in protection against T1D onset in an STZ-induced diabetes model." (PMID 32295112, 2020). "Whilst a number of agents can ameliorate (e.g. angiotensin converting enzyme [ACE] inhibitors, perhexiline, statins and insulin) or circumvent (e.g. nitrite and sGC activators) NO• resistance, nitroxyl (HNO) donors offer a novel opportunity to circumvent NO• resistance in diabetes." (PMID 32508651, 2020). "The DR group had a higher proportion of older and female participants and those using insulin, a higher prevalence of hypertension, and longer duration of diabetes than the non-DR group did." (PMID 32104706, 2020). "Interestingly, the beneficial actions of oestrogens on beta cells could explain why the male predominance in diabetes prevalence is not restricted to type 2 diabetes but also applies to insulin-deficient forms of diabetes, such as type 1 diabetes, that are diagnosed post puberty." (PMID 31754750, 2020). "TZD as treatment for patients with obesity and without diabetes reduces circulating levels of inflammatory cytokines and other pro-inflammatory markers, which are accompanied by improved insulin sensitivity." (PMID 32708786, 2020). "•Unemployment, lack of family/social support, duration of diabetes of >10 years, poor knowledge of diabetes, taking insulin and taking metformin plus glibenclamide were identified as factors affecting glycemic control." (PMID 32528672, 2020). "As a result of this effect on regulatory pathways, TZDs improve insulin sensitivity, glucose tolerance, and the lipidemic profile in T2D as well as in obesity without diabetes." (PMID 32708786, 2020). "The use of connected insulin pens alongside CGM may have the potential to facilitate and improve diabetes management." (PMID 32003590, 2020). "Type 2 DM, which is mainly provoked by the degradation of produced insulin, affects more people in contrast with other types of diabetes, and patients do not rely on exogenous insulin for the prevention of ketonuria as well as ketosis." (PMID 33228164, 2020). "As one of the treatment methods that are expected to cure diabetes completely, one main challenges in gene therapy is that fully mature β-cells can not be obtained for insulin replacement therapy." (PMID 32850735, 2020). "It is reported that Rhesus macaques (Macaca mulatto) received 140 mg/kg of STZ developed T1D and became insulin dependent for more than 1 year without apparent reversal of diabetes." (PMID 32318663, 2020).